TLE7 (TLE family member 7)
Synonyms: chico
Gene: Protein-coding gene on chromosome 16 (71,429,980 to 71,442,054, reverse strand). Ensembl gene ENSG00000260734.
Gene Ontology:
Molecular function: transcription corepressor activity
Biological process: negative regulation of canonical Wnt signaling pathway; negative regulation of DNA-templated transcription; regulation of DNA-templated transcription
Cellular component: nucleus; transcription regulator complex
Homologues: Orthologues: chimpanzee TLE7 (99% identical), macaque TLE7 (93% identical), dog TLE7 (68% identical), pig TLE7 (67% identical), rabbit TLE7 (67% identical), rat Tle7 (64% identical), mouse Tle7 (61% identical), tropical clawed frog tle2 (34% identical), zebrafish tle2a (33% identical), zebrafish tle2b (32% identical), zebrafish tle2c (5% identical). Paralogues in human: TLE2 (35% identical), TLE1 (34% identical), TLE4 (33% identical), TLE3 (33% identical), TLE6 (28% identical), TLE5 (3% identical).